ROMO1 (reactive oxygen species modulator 1)
Diseases named in the same sentence as ROMO1 in open-access papers (continued):
Sharing a sentence is not in itself a finding about the gene and the disease.
tumor (continued). "Moreover, Chung el al showed that ROMO1 might be a principal factor in the deregulation of nuclear factor-κB and related pathways that contribute to tumour cell proliferation and invasion." (PMID 33302957, 2020). "Here, we used tumor subtype analysis and an energetic co-expression network algorithm of WGCNA and MEGENA to identify a signal dominated by the ROMO1 to predict PCa prognosis." (PMID 34996995, 2022). "Further, the expression of NDUFB7, AURKAIP1, ROMO1, SCAND1, GADD45GIP1, and NDUFA13 was upregulated in the four tumor subtypes compared with normal adjacent tissue." (PMID 34996995, 2022). "In the current study, only lymphatic invasion of primary tumor, not vascular invasion, was shown to correlate with Romo1 expression." (PMID 28472059, 2017). "Even though a number of studies have reported a critical role for Romo1 in various cancers’ cell proliferation, Romo1 expression was not significantly related to tumor size or T staging in our cohort." (PMID 28472059, 2017). "Although it is unclear why Romo1 does not affect cell proliferation and tumor size in CRC unlike in other cancers, the results from both the analysis of the patients’ clinical outcomes and the in vitro study accorded with each other." (PMID 28472059, 2017). "Romo1 expression was related to LNR and lymphatic invasion of primary tumors (p values were 0.025 and 0.043 respectively), but not other parameters including age, gender, N stage, tumor size, and tumor differentiation." (PMID 28472059, 2017).
cancer (20 papers, 2017 to 2025). A tumor composed of atypical neoplastic, often pleomorphic cells that invade other tissues. "Dysregulation of ROMO1 has been implicated in a variety of cancers, but its specific involvement in HPV-driven malignancy has not been critically evaluated." (PMID 41148844, 2025). "Since ROMO1 is associated with the level of oxidative stress and ROS production in cancer cells, and by regulating its expression, it can reduce cancer symptoms and better response to chemotherapy." (PMID 39727991, 2024). "Subsequent studies have proved the underlying roles of aberrant ROMO1 in the cancer development and treatment." (PMID 37386404, 2023). "Romo1 produces ROS by oxidative stress and eventually causes cell hyperplasia and cancer cell invasion." (PMID 33259495, 2020). "Another report demonstrated that Romo1 induced not only cancer cell proliferation but also cancer cell invasion via deregulated NF-kB signaling pathway by showing this pathway’s downregulation caused by Romo1 knockdown." (PMID 28472059, 2017). "Romo1 overexpression not only had consistently been associated with cancer invasiveness in a variety of in vitro studies and in a retrospective study with HCC patients, but also was shown to be essential in lymphatic metastasis in the current study." (PMID 28472059, 2017). "The bioinformatics analysis results suggest that the upregulation of ROMO1 may be linked to the development and progression of selected gastrointestinal cancers and may be associated with a faster progression of these cancers." (PMID 39727991, 2024). "The underlying roles of ROMO1 methylation in various cancers remain largely unclear." (PMID 39727991, 2024). "As ROS regulating protein, Romo1 is associated with the level of oxidative stress and the production of ROS in cancerous cells, considering that one of the most important causes for the incidence of cancer is the increase of free radicals and ROS." (PMID 35461390, 2022). "Furthermore, the mechanism by which Romo1 affects cancer invasiveness is reported to be associated with epithelial-mesenchymal transition (EMT) markers and the NF-kB signaling pathway." (PMID 28472059, 2017). "We suppose that Romo1 induces cancer invasiveness and consequently lymphatic invasion, which is an important process of lymphatic metastasis; Lymphatic metastasis is a key reason for the poor survival associated with highly expressed Romo1." (PMID 28472059, 2017). "Since the major cause of cancer mortality is metastasis, the patients’ survival rate could be improved by targeting Romo1." (PMID 28472059, 2017). "ROMO1 is significantly upregulated in gastrointestinal cancers and closely associated with clinicopathological features, which may play an essential role in the development of these cancers." (PMID 39727991, 2024). "We also propose that ROMO1 represents a potential stage-specific biomarker and therapeutic target in HPV-associated cancers." (PMID 41148844, 2025). "In some cancer types, elevated ROMO1 expression correlates with enhanced proliferation and invasion, likely through the generation of sub-lethal ROS levels that activate mitogenic pathways such as ERK and NF-κB." (PMID 41148844, 2025). "In conclusion, the expression of ROMO1 was significantly higher in the early stages of the disease; as the cancer progresses the expression of the protein decreases." (PMID 40427422, 2025). "Understanding ROMO1’s dual functionality provides insight into its potential as a therapeutic target for oxidative stress-related disorders, especially cancer progression." (PMID 40427422, 2025). "This dynamic mirrors ROMO1’s dual role in cancer biology, which appears to be highly context-dependent." (PMID 41148844, 2025). "By placing ROMO1 within this framework, we identify it as both a mediator and potential marker of stage-specific vulnerabilities in HPV-associated cancers." (PMID 41148844, 2025).
cancer (continued). "Early lesions, typically characterized by episomal HPV and strong E6/E7 expression-exhibited robust ROMO1 staining, while more invasive cancers with integrated HPV genomes showed diminished ROMO1." (PMID 41148844, 2025). "This review highlights the current understanding of how HPV oncoproteins impact mitochondrial structure and function, emphasizes the role of ROMO1 in this context, and compares findings with other cancer types." (PMID 41148844, 2025). "Exploring this dichotomy across cancer types can inform how HPV co-opts ROMO1 for its own oncogenic advantage." (PMID 41148844, 2025). "ROMO1 expression was observed to differ among cancer types and to have high expression in gastrointestinal cancers." (PMID 39727991, 2024). "ROMO1, a protein that regulates ROS production, has been shown to play an essential role in many types of cancer." (PMID 39727991, 2024). "The idea of analyzing the expression of Romo1 in EC and OC comes from the evidence of its role in the process of invasion and also the progression of cancer cells." (PMID 35461390, 2022). "Reactive oxygen species modulator 1 (Romo1) is known to play a crucial role in cancer cell invasion, inflammation, cellular senescence, mitochondrial protein translocation, mitochondrial dynamics, and mitochondrial redox sensing." (PMID 35806412, 2022). "Located in the mitochondrial membrane, this novel protein is a major regulator of the production of intracellular reactive oxygen species (ROS), and Romo1-induced ROS play a significant role in cell proliferation in both cancer and normal cells." (PMID 34956890, 2021). "As Romo1 is located in the mitochondrial membrane, it was primarily localized in the cytoplasm of cancer cells, as expected." (PMID 34956890, 2021). "Romo1 is a major regulator of intracellular ROS production, and Romo1-induced ROS are indispensable for the proliferation of normal and cancer cells." (PMID 34956890, 2021). "Romo1 has been reported to play a large role in cancer cell proliferation through myc, ERK activation and activation of NF-kB." (PMID 32825500, 2020). "Romo1, a novel mitochondrial protein, is the key regulator of mitochondrial ROS production and an essential factor for cancer cell proliferation and invasion." (PMID 32825500, 2020). "It was shown that in physiological states ROMO1-derived ROS were indispensable for the proliferation of both normal and cancer cells, respectively." (PMID 33302957, 2020). "Although the physiological functions of Romo1 have been studied for the past few years, the role of Romo1 in cancer remained unclear." (PMID 31945745, 2020). "It has been proven that increased ROMO1 expression, in response to external stress, enhances cellular ROS levels; its expression is also essential for cancer cell proliferation." (PMID 31480133, 2020). "Recent studies have shown that the ROMO1 gene product are highly expressed in cancer cells and triggers sustained inflammatory response." (PMID 31443466, 2019). "Romo1-induced ROS is reported to contribute cancer cell proliferation through extracellular signal-regulated kinases (ERK) activation and constitutive activation of nuclear factor kappa B (NF-kB)." (PMID 28472059, 2017). "Additional studies are needed on the different roles of Romo1 in the cell proliferation of different cancers." (PMID 28472059, 2017). "Upregulation of Romo1, which is the key regulator of mitochondrial reactive oxygen species (ROS) release, was observed in various cancer cells and reported to be crucial for cancer cell proliferation and invasion." (PMID 28472059, 2017). "In a previous study, intracellular ROS levels and cancer cell growth decreased with Romo1 knockdown." (PMID 28472059, 2017). "Reactive oxygen species modulator-1 (Romo1) is a novel mitochondrial protein that was first cloned in 2006 as a newly emerged gene in cancer tissues that had become resistant during chemotherapy." (PMID 28472059, 2017).
cancer (continued). "The current study showed that high Romo1 expression in cancer tissues is significantly related to early recurrence and poor survival in CRC patients who had curative resection (n = 190)." (PMID 28472059, 2017). "Cancer invasiveness appeared to be a key reason for the poor survival related to highly expressed Romo1." (PMID 28472059, 2017). "Reactive oxygen species modulator-1 (Romo1) is a novel protein that has been reported to be crucial for cancer cell proliferation and invasion." (PMID 28472059, 2017). "ROMO1 KD triggers G1 arrest in several cancer cell lines including H1299 and A549 cells." (PMID 40076565, 2025). "Although ROMO1 has been studied in the context of other cancers, its mechanistic regulation by HPV oncoproteins remains unclear." (PMID 41148844, 2025). "While ROMO1 is overexpressed in many cancers and correlates with poor prognosis, recent data suggest that HPV-associated cervical lesions exhibit a unique biphasic expression pattern, with high ROMO1 levels in early stages and reduced expression in advanced tumors." (PMID 41148844, 2025). "This pattern differs from what has been reported in several non-HPV-related cancers, where high ROMO1 expression is usually associated with more advanced disease." (PMID 41515519, 2025). "We believe that ROMO1 could be used as a potential biomarker in many medical fields, especially in cancer progression." (PMID 40427422, 2025). "ROMO1, a redox-sensitive mitochondrial protein, plays a dual role—initially buffering oxidative stress in early stages but potentially becoming downregulated as cancer progresses." (PMID 41148844, 2025). "Like MTLN, ROMO1 gene expression is elevated in many cancers." (PMID 40076565, 2025). "In addition, analysis of ROMO1 mRNA expression between normal tissues and cancers using GEPIA revealed that ROMO1 showed significantly higher expression in COAD, ESCA, PAAD, LIHC, and STAD." (PMID 39727991, 2024). "More research is required to elucidate the mechanism and determine whether ROMO1 has a specific function in various cancer types." (PMID 39727991, 2024). "Functional tests on cell lines derived from these particular gastrointestinal cancers can also be performed in vitro to evaluate the impact of the ROMO1 gene and other factors, like potential drugs, on the expression of these genes and the development and progression of the cancer." (PMID 39727991, 2024). "We used the TIMER database to examine the expression of ROMO1 in different cancer types." (PMID 39727991, 2024). "ROMO1 has been shown to play an important role in many types of cancer." (PMID 39727991, 2024). "Through evaluating the profiles of ROMO1 in cancer samples, several groups independently demonstrated that ROMO1 could be served as a promising diagnostic and prognostic biomarker." (PMID 37386404, 2023). "In addition, Romo1-induced ROS are related to the drug resistance of 5-fluorouracil (5-FU), and Romo1 overexpression induces invasive activity in various cancer cells." (PMID 34956890, 2021). "ROMO1 is therefore considered an attractive cancer treatment target." (PMID 34766130, 2020). "It was observed that Romo1 is up-regulated in various cancers." (PMID 32825500, 2020). "With more extensive efforts to define the exact effects and functions of Romo1, Romo1 inhibitors could be developed and used as new anti-cancer agents." (PMID 28472059, 2017). "Through further study to determine the exact functions of Romo1, other favorable targets for cancer treatment might be found." (PMID 28472059, 2017). "In order to validate that Romo1 induces high lymphatic metastatic tendency, we conducted an in vitro study that revealed the role of Romo1 in cancer invasiveness; specifically, knockdown of Romo1 decreased cancer cell invasion." (PMID 28472059, 2017).
cancer (continued). "Regulating mitochondrial ROS release or production rather than eliminating ROS already produced by mitochondria could be another method of preventing cancer cell invasion, and for this reason, we suggest Romo1 as a promising target of cancer treatment." (PMID 28472059, 2017). "It is thought that Romo1 induces cancer invasiveness, therefore promotes lymphatic invasion of primary tumor, which is an important process of lymphatic metastasis; Lymphatic metastasis induced by Romo1 is thought to be a key reason for the poor survival associated with Romo1 overexpression." (PMID 28472059, 2017). "ROMO1 expression is initially upregulated in early HPV infection, likely as a compensatory response to rising ROS, but becomes suppressed as cancer progresses—potentially due to HPV genome integration or epigenetic silencing." (PMID 41148844, 2025). "Collectively, these findings highlight that ROMO1 promotes HCC cell invasiveness by increasing ROS levels, supporting its potential role as a therapeutic target for limiting cancer metastasis." (PMID 40427422, 2025). "Another mitochondrial-localized protein, ROS Modulator 1 (ROMO1), has been shown to be essential to cell cycle progression in cancer- and non-cancer cells via the generation of ROS from mitochondrial complex III." (PMID 40076565, 2025). "Mechanistically, too much ROS produced by ROMO1 can stimulate redox-sensitive oncogenic pathways (NF-κB, MAPK/ERK, TGF-β), encourage the change of epithelium to mesenchymal tissue, and stimulate the migration and multiplication of cancer cells." (PMID 41515519, 2025). "The absence of functional studies specifically addressing ROMO1 silencing in these cancer types highlights an important gap in our understanding and represents a promising avenue for future investigation." (PMID 41148844, 2025). "Serum TFF-3, Romo-1 and NF-кB levels were significantly higher in patients with EC and OC than those without cancer." (PMID 35461390, 2022). "Firstly, the role of ROMO1 has not been validated experimentally in vivo and in vitro, and secondly, the fact that the number of cancer samples and normal samples are not identical to each other has led to some preference in our data." (PMID 34996995, 2022). "We discovered that serum TFF3, Romo-1 and NF-кB levels were significantly higher in patients with EC or OC compared to those without cancer instead of serum SFRP4 levels that were significantly lower in cancer groups compared to the control one." (PMID 35461390, 2022). "Taken together, we propose that targeting Romo1 can be a sensitizer of TRAIL and it may be a new therapeutic strategy for cancer." (PMID 32825500, 2020). "Even when including the 31 patients, Romo1 was shown to be correlated with high LNR, which is reported to be superior to the previous N staging system in predicting and stratifying the prognosis of a number of cancers including CRC in recent studies." (PMID 28472059, 2017). "Romo1 protein is essentially localized in the cytoplasm of cancer cells, and the Romo1 levels were not normally distributed (average: 13.6, range, 0 to 30)." (PMID 28472059, 2017). "It is unclear why, despite the same results from in vitro studies regarding Romo1’s role in cancer invasiveness, lymphatic metastasis did not appear to relate to Romo1 overexpression in other cancer cohorts." (PMID 28472059, 2017). "Romo1 was primarily localized to the cytoplasm of cancer cells, regardless of type of NSCLC." (PMID 33259495, 2020).
Gastrointestinal Tract Cancers (1 paper, 2024). "Overall, these results indicate that ROMO1 expression is upregulated in gastrointestinal tract cancers." (PMID 39727991, 2024). "However, the biological function of ROMO1 is still poorly understood in gastrointestinal system cancers." (PMID 39727991, 2024).
GI tumors (1 paper, 2024). "Thus, our results suggest that methylation level and GI tumors both play a significant role in controlling the expression of the ROMO1 complex gene." (PMID 39727991, 2024). "To determine whether ROMO1 was differentially expressed among pathological stages, we first analyzed the correlations between mRNA expression of ROMO1 and pathological stages among gastrointestinal tumors using GEPIA2." (PMID 39727991, 2024).
infection (1 paper, 2025). The state of being infected such as from the introduction of a foreign agent such as serum, vaccine, antigenic substance or organism. "Emerging evidence suggests that HPV may regulate ROMO1 expression during infection and transformation, contributing to stage-dependent differences in redox stress and metabolic vulnerability." (PMID 41148844, 2025).
ROMO1 also shares sentences with these, for which no sentence is quoted: gastric cancer (2 papers); asthma (1); bacteremia (1); basal cell carcinoma (1); colon adenocarcinoma (1); coronary diseases (1); developmental disabilities (1); endometrial cancer (1); esophageal carcinoma (1); hepatoblastoma (1); mitochondrial encephalomyopathy (1); myocardial infarction (1); obstructive sleep apnea syndrome (1); pancreatic adenocarcinoma (1); proliferative diabetic retinopathy (1); respiratory disease (1).